THSD7A (thrombospondin type 1 domain containing 7A)
Description:
[Thrombospondin type-1 domain-containing protein 7A]: Plays a role in actin cytoskeleton rearrangement. [Thrombospondin type-1 domain-containing protein 7A, soluble form]: The soluble form promotes endothelial cell migration and filopodia formation during sprouting angiogenesis via a FAK-dependent mechanism.
Synonyms: KIAA0960
Tractability: Antibody: UniProt places it where antibodies can reach, with high confidence; its Gene Ontology location is reachable by antibodies, with high confidence; UniProt predicts a signal peptide or a membrane-spanning region. PROTAC: its protein half-life has been measured.
Gene: Protein-coding gene on chromosome 7 (11,370,365 to 11,832,198, reverse strand). Ensembl gene ENSG00000005108.
Subcellular location: Cell membrane (Thrombospondin type-1 domain-containing protein 7A); Cell projection; Secreted (Thrombospondin type-1 domain-containing protein 7A, soluble form)
Pathways (Reactome):
Disease: Defective B3GALTL causes PpS
Metabolism of proteins: O-glycosylation of TSR domain-containing proteins
Gene Ontology:
Molecular function: protein binding
Biological process: actin cytoskeleton organization
Cellular component: extracellular region; plasma membrane
Genetic constraint (gnomAD): Loss-of-function variants: 91 observed, 216.47 expected, observed/expected ratio (o/e) 0.42, 90% interval 0.35 to 0.5. The synonymous counts are far from expectation, so gnomAD's model fits this gene poorly and the ratio says little. Missense variants: 2,231 observed, 2,057.1 expected, observed/expected ratio (o/e) 1.08, 90% interval 1.05 to 1.12. Synonymous variants: 918 observed, 728.92 expected, observed/expected ratio (o/e) 1.26, 90% interval 1.19 to 1.33.
Homologues: Orthologues: chimpanzee THSD7A (99% identical), macaque THSD7A (98% identical), dog THSD7A (94% identical), pig THSD7A (93% identical), rat Thsd7a (91% identical), mouse Thsd7a (91% identical), rabbit THSD7A (89% identical), guinea pig THSD7A (86% identical), tropical clawed frog thsd7a (76% identical), zebrafish thsd7aa (69% identical), zebrafish thsd7ab (62% identical). Paralogues in human: THSD7B (49% identical), SPON1 (13% identical), SPON2 (5% identical).
Diseases named in the same sentence as THSD7A in open-access papers:
THSD7A is named in the same sentence as 83 diseases in open-access papers, as found by Europe PMC text mining. Sharing a sentence is not in itself a finding about the gene and the disease. The quoted sentences say what the papers report.
membranous nephropathy (62 papers, 2015 to 2026). "This has been nicely demonstrated for a case with thrombospondin type-1 domain-containing 7A (THSD7A)-associated membranous nephropathy (MN) who had a concomitant gallbladder carcinoma." (PMID 39119062, 2024). "The aim of this review is a comprehensive analysis of the current literature concerning the role of autoantibodies (anti-PLA2R/anti-THSD7A) in the pathogenesis of membranous nephropathy and their use in the diagnostic and therapeutic process monitoring." (PMID 35564696, 2022). "Phospholipase A2 receptor 1 (PLA2R1) and thrombospondin type-1 domain-containing 7A (THSD7A) are the two major pathogenic antigens for membranous nephropathy (MN)." (PMID 34229600, 2021). "Membranous Nephropathy (MN) is an autoimmune disease associated with antibodies against podocyte proteins: M-type phospholipase A2 receptor (PLA2R1) or thrombospondin type-1 domain-containing 7A (THSD7A) in 70 and 3% of patients, respectively." (PMID 31998325, 2019). "Additionally, THSD7A has been shown to be aberrantly expressed in a variety of cancers and autoantibodies against THSD7A are a frequent cause of a paraneoplastic autoimmune kidney disease, secondary membranous nephropathy." (PMID 41532547, 2026). "Autoantibodies against THSD7A are also a cause of idiopathic (primary) membranous nephropathy." (PMID 41532547, 2026). "Studies have also proved that THSD7A is closely associated with membranous nephropathy." (PMID 36506585, 2022). "Furthermore, 21% of patients with IMN associated with THSD7A were found to have tumors within 3 months of being diagnosed with membranous nephropathy." (PMID 32117644, 2020). "Among antigens that are expressed in patients with membranous nephropathy thrombospondin type 1 domain-containing 7A and neural epidermal growth factor-like-1 are often reported in patients with underlying malignancies." (PMID 40352576, 2025). "Pathogenic mechanisms in NS: Pathogenic antibody reservoir: In membranous nephropathy, class-switched memory B cells are an important source of pathogenic IgG4 antibodies such as anti-PLA2R and anti-THSD7A." (PMID 40852718, 2025). "Anti-THSD7A antibodies are found in approximately 10% of PLA2R-negative membranous nephropathy patients." (PMID 40852718, 2025). "THSD7A, a transmembrane protein expressed on podocytes, is the target autoantigen in ~3% of cases of primary membranous nephropathy." (PMID 40358163, 2025). "Some cases were subjected to specific histochemical (Congo red, n=30) or IHC stains, including PLA2R and THSD7A (n=21 each for membranous nephropathy), and DNAJB9 (n=9 for suspected fibrillary glomerulonephritis)." (PMID 38538076, 2025). "Rituximab has emerged as a primary therapeutic option for idiopathic membranous nephropathy, particularly following the identification of various pathogenic autoantibodies, predominantly anti-PLA2R and anti-THSD7A." (PMID 38540991, 2024). "Following the discovery of podocyte phospholipase A2 receptor and thrombospondin type-1 domain-containing 7A, various potential target antigens for membranous nephropathy (MN) have been reported one after another." (PMID 38892120, 2024). "Current studies on THSD7A-related diseases mainly include osteoporosis, membranous nephropathy, and tumors." (PMID 36506585, 2022). "The etiology of primary membranous nephropathy is associated with the production of autoantibodies directed against podocyte antigens, primarily M-type phospholipase A2 receptor (PLA2R) or thrombospondin type-I domain-containing 7A (THSD7A)." (PMID 36614013, 2022). "Serum and tissue-based tests using phospholipase A2 receptor 1 (PLA2R) and thrombospondin type-1 domain containing 7A (THSD7A) are established immune biomarkers for the diagnosis of primary membranous nephropathy (PMN)." (PMID 33413188, 2021).
membranous nephropathy (continued). "Membranous nephropathy (MN) is an autoimmune disease caused by autoantibodies against the podocyte antigens phospholipase A2 receptor 1 (PLA2R1) and thrombospondin type 1 domain containing protein 7A (THSD7A) in 80% and 2–3% of patients, respectively." (PMID 34376704, 2021). "Thrombospondin type 1 domain containing 7A (THSD7A) was recently identified target autoantigen in membranous nephropathy (MN)." (PMID 31443644, 2019). "Thrombospondin type 1 domain containing 7A (THSD7A) was recently identified as a new autoantigen in membranous nephropathy (MN)." (PMID 31443644, 2019). "These alterations are consistent with stage II membranous nephropathy associated with IgA nephropathy stained positive for PLA2R and THSD7A." (PMID 31663595, 2019). "Malignancies should be screened and closely monitored in THSD7A-positive membranous nephropathy patients." (PMID 29623759, 2018). "Thsd7a is mainly expressed in cell membrane, which is entirely concordant with the previous findings in Membranous Nephropathy, and there is a little expression in the cytoplasm, which was never sported before." (PMID 28947992, 2017). "It was proposed that Thsd7a protein actively participated in Osteoporosis, Membranous Nephropathy and Obesity, and has significantly genetic variations in some exons." (PMID 28947992, 2017). "At present, the research of Thsd7a is mainly focused on Osteoporosis, Membranous Nephropathy and Obesity." (PMID 28947992, 2017). "Although the pathogenic role of autoantibodies targeting the podocyte protein THSD7A in membranous nephropathy (MN) is well described, the consequences of autoantibody binding for podocyte homeostasis and the function of THSD7A remain unclear." (PMID 41746732, 2026). "Interestingly, both molecules identified as cargoes of filopodia-regulating exosomes are associated with disease: endoglin with hereditary hemorrhagic telangiectasia, and THSD7A with a kidney disease called secondary membranous nephropathy." (PMID 41532547, 2026). "In 2014, the involvement of another candidate with the responsible antigen, thrombospondin type-1 domain-containing 7A (THSD7A), was also revealed, and an autoantibody against THSD7A was reported to be positive in approximately 5% of patients with primary membranous nephropathy." (PMID 40100934, 2025). "Furthermore, several other groups investigated the possible relationship between THSD7A expression in malignant diseases and the development of membranous nephropathy." (PMID 36673031, 2023). "Membranous nephropathy (MN) is an organ-restricted autoimmune disease mainly caused by circulating autoantibodies against podocyte antigens, including the M-type phospholipase A2 receptor (PLA2R) and thrombospondin domain-containing 7A (THSD7A)." (PMID 34337081, 2021). "The identification of the phospholipase A2 receptor 1 (PLA2R) and thrombospondin type-1 domain-containing protein 7A (THSD7A) as podocyte antigens in adult patients with membranous nephropathy (MN) has strongly impacted both experimental and clinical research on this disease." (PMID 33825066, 2021). "What is the role of THSD7A in membranous nephropathy and malignancies?" (PMID 31447839, 2019). "The positive rate of THSD7A was very low in secondary membranous nephropathy (SMN)." (PMID 29623759, 2018). "Furthermore, THSD7A is involved in the pathogenesis of membranous nephropathy." (PMID 36673031, 2023). "Through serum analysis of patients with membranous nephropathy, the urinary protein level was positively correlated with the titer of THSD7A, and the serum THSD7A level was decreased with the activity degree in a course, which might affect the activity degree of the disease." (PMID 36506585, 2022). "Furthermore, animal studies suggested that the binding of a human THSD7A antibody with mouse THSD7A leads to proteinuria, which may be one of the pathogenesis of membranous nephropathy." (PMID 36506585, 2022).
membranous nephropathy (continued). "Thrombospondin type-I domain-containing 7A (THSD7A) was identified as the target antigen in about 10% of patients with PLA2R-negative MN in European and North American populations, but THSD7A-associated membranous nephropathy has a low prevalence in Chinese patients." (PMID 34508140, 2021). "Moreover, malignancies are also found in patients with THSD7A-positive membranous nephropathy." (PMID 29623759, 2018). "Another renal AID, i.e., membranous nephropathy (MN), is characterized by the presence of autoantibodies targeting phospholipase A2 receptor 1 (PLA2R1) and thrombospondin type-1 domain-containing protein 7A (THSD7A)." (PMID 40422256, 2025). "Such important biomarkers include anti-PLA2R and anti-THSD7A antibodies, which are specific to the primary form, as well as exostosin (EXT-1 and EXT-2), as markers of membranous nephropathy secondary to autoimmune diseases, particularly LN." (PMID 39682589, 2024). "In membranous nephropathy, IgG4 antibodies against PLA2R or THSD7A penetrate the glomerular loop and glomerular basal membrane and induce the cytotoxicity of podocytes and leakage of proteins from vessels to renal tubules." (PMID 38980226, 2024). "In approximately 80% of cases, membranous nephropathy is primary, mediated by IgG autoantibodies primarily targeting podocyte antigens (PLA2R, THSD7A, etc.)." (PMID 38540991, 2024). "In the remaining cases (70–80%), primary membranous nephropathy (PMN) is observed where the main role is played by PLA2R (phospholipase A2 receptor) and THSD7A (Human thrombospondin, type I, domain containing 7A) antigen." (PMID 35564696, 2022). "The discovery of target antigens has created a greater heterogeneity in membranous nephropathy that can be defined by detecting autoantibodies using serological methods or by renal expression of PLA2R and THSD7A in renal biopsy specimens." (PMID 35564696, 2022). "Patients with membranous nephropathy have autoantibodies against PLA2R (up to 80%), or THSD7A (up to 2%)." (PMID 31395435, 2020). "Most scenarios of primary membranous nephropathy are mediated by autoantibodies to M type Phosphoplipase A2 receptor (PLA2R) (95%) and Thrombospondin type 1 domain containing 7a (THSD7a) receptor, a podocyte antigen (3–5%)." (PMID 31611870, 2019). "Thrombospondin type‐1 domain‐containing 7A (THSD7A) is a large transmembrane glycoprotein like PLA2R1, and again like PLA2R1 was recently identified as a novel podocyte foot process protein targeted by autoimmunity in membranous nephropathy." (PMID 40698593, 2025). "This case series identified 23 patients with NELL-1 (+), PLA2R (−), and THSD7A (−) membranous nephropathy (MN) from a cohort of 531 non-SLE MN patients." (PMID 40978725, 2025). "•In membranous nephropathy, serum circulating autoantibodies against PLA2R and THSD7A, immunohistochemical tissue markers for glomerular PLA2R, THSD7A and specific types of immunoglobulin G (IgG) may be used for identifying underlying malignancies." (PMID 35220046, 2022). "The pathogenesis of membranous nephropathy (MN) has been confirmed since the discovery of autoantibodies against podocyte M-type phospholipase A2 receptor (PLA2R) and thrombospondin type 1 domain-containing protein 7 A (THSD7A)." (PMID 35723077, 2022). "A renal biopsy revealed EXT1-positive, PLA2R/THSD7A-negative, membranous nephropathy with IgG and C3 deposition." (PMID 33655949, 2021). "Autoantibodies in membranous nephropathy are directed against at least two podocyte-specific membrane proteins with extracellularly exposed regions including phospholipase A2 receptor (PLA2R) and thrombospondin type-1 domain-containing 7A (THSD7A)." (PMID 33763057, 2021). "Numbers of patients with enhanced granular expression of IgG4 among thrombospondin type-1 domain-containing 7A (THSD7A)-positive, M-type phospholipase A2 receptor (PLA2R)-positive, and THSD7A/PLA2R-negative patients with idiopathic MN and secondary membranous nephropathy (MN)." (PMID 26393352, 2015).
membranous nephropathy (continued). "Incomplete disease coverage: The T-cell paradigm primarily explains minimal change disease (MCD) pathogenesis but fails to account for antibody-mediated diseases like membranous nephropathy, where specific autoantibodies (anti-PLA2R, anti-THSD7A) are the primary pathogenic drivers." (PMID 40852718, 2025). "Secondly, the latest guidelines do not require the measurement of autoantibodies for PLA2R or THSD7A, which may be useful for diagnosing membranous nephropathy." (PMID 40100934, 2025). "Not all patients were tested for THSD7A-, NELL1-, or EXT1/2-related antibodies; otherwise, this would have affected the generalizability of the results (other antibody-related membranous nephropathy)." (PMID 41041325, 2025).
autoimmune disease (19 papers, 2018 to 2025). A disorder resulting from loss of function or tissue destruction of an organ or multiple organs, arising from humoral or cellular immune responses of the individual to their own tissue constituents. "The disease can be primary (autoantibodies against PLA2R/THSD7A) or secondary (associated with factors such as cancer, infection, drugs, or autoimmune diseases); this distinction has prognostic and therapeutic implications." (PMID 41373530, 2025). "Primary membranous nephropathy (PMN) is a renal-specific autoimmune disease caused by circulating autoantibodies that target glomerular podocyte antigens (PLA2R/THSD7A)." (PMID 31781684, 2019). "PMN is now recognized as an autoimmune disease caused by the discovery of specific antigens such as the anti-phospholipase A2 receptor (PLA2R) antibody and thrombospondin type-1 domain-containing 7 A (THSD7A)." (PMID 38448810, 2024). "The recent findings on the role of circulating antibodies recognizing podocyte-specific antigens (PLA2R/THSD7A) in the pathogenesis of primary MN have clearly identified this primary glomerulonephritis as an autoimmune disease." (PMID 31781684, 2019). "Anti-PLA2R1 or anti-THSD7A autoantibodies have been proposed as biomarkers of autoimmune disease activity and their blood levels should be regularly monitored in pMN to evaluate disease activity and predict outcomes." (PMID 29511687, 2018). "Primary MN is related to the autoimmune disorders caused by the presence of circulating antibodies against native podocyte antigens NEP, PLA2R1, and THSD7A or by antibodies developed against external antigens such as cationic bovine serum albumin (BSA) or aryl sulfatase." (PMID 29511687, 2018). "MN is now recognized as a renal-limited autoimmune disease, with antibodies against PLA2R (aPLA2Rab) detected in 70% to 80% of cases and antibodies against thrombospondin type-1 domain-containing 7A (THSD7A) in 2% to 5% of patients." (PMID 39234257, 2024). "In most patients, MN is an autoimmune disease mediated by autoantibodies directed against phospholipase A2 receptor (PLA2R) or, more unusually, thrombospondin type-1 domain-containing 7A (THSD7A)." (PMID 36176440, 2022). "With the discovery of autoantigen neutral endopeptidase, PLA2R, THSD7A, etc., IMN was considered as an autoimmune disease." (PMID 31443644, 2019). "For example, nephrologists appear to adopt a more aggressive malignancy workup for the antigens associated with malignancy, NELL1 and THSD7A, but not for EXT1/2 which has been associated with autoimmune diseases." (PMID 40500560, 2025). "It is primarily an autoimmune disease mediated by circulating autoantibodies targeting podocyte-expressed antigens such as phospholipase A2 receptor (PLA2R), thrombospondin type-1 domain-containing 7A (THSD7A), and neural epidermal growth factor-like 1 protein (NELL-1)." (PMID 40642691, 2025). "Interestingly, the TGFBR3, THSD7A, and NTNG1 MNTAgs also exhibit podocyte preference expression, supporting the important pathological contributions of podocyte injury to the kidney-limited autoimmune disease of MN." (PMID 40149392, 2025).